TNF (tumor necrosis factor)
Diseases named in the same sentence as TNF in open-access papers (continued):
Sharing a sentence is not in itself a finding about the gene and the disease.
emphysema (116 papers, 2004 to 2025). "Research indicates that myrcophenostatin protects against COPD-associated inflammation and emphysema by regulating genes for pro-inflammatory mediators like TNF-α, IL-1β, G-CSF, and KC." (PMID 39950029, 2025). "In particular, TNF-α has proinflammatory and prooxidative actions, and its overexpression has been associated with emphysema." (PMID 37494277, 2023). "In correlation analyses, we found evidence of a weak correlation between the two inflammatory markers significantly associated with emphysema, TNFα and IL-1β (rho=0.13, p<0.001)." (PMID 33936110, 2021). "Further, we found a strong association between elevated TNFα and IL-1β with emphysema in models adjusted for age and sex." (PMID 33936110, 2021). "Elevated TNFα (adjusted odds ratio (aOR): 1.89 [95%CI: 1.26-2.83], p=0.002) and IL-1β (aOR: 1.72 [95%CI: 1.14-2.59], p=0.009) were associated with emphysema in base models with adjustment for age and sex only." (PMID 33936110, 2021). "In the present study, we found an independent association between two markers of systemic inflammation, TNFα and IL-1β, and radiographic emphysema in PLWH." (PMID 33936110, 2021). "Remodeling of the ECM by various MMPs is modulated by pro-inflammatory cytokines such as TNFα, IL-1α, and TGFβ, which are implicated in the pathogenesis of emphysema." (PMID 31234847, 2019). "The TGFB1 rs2241718 and MMP9 rs3918242 SNPs were associated with centrilobular emphysema (p = 0.022 and p = 0.008), and the TNF rs1800629 SNP with paraseptal emphysema (p = 0.017)." (PMID 23734748, 2013). "The TGFB1 rs2241718 and MMP9 rs3918242 SNPs were associated with centrilobular emphysema (p = 0.022 and p = 0.008, respectively), and the TNF rs1800629 SNP was associated with paraseptal emphysema (p = 0.017)." (PMID 23734748, 2013). "While IL-6 and MMP-7 were directly associated with F-950, TNF-α was inversely related to emphysema severity." (PMID 19718453, 2009). "The CS-induced emphysema was associated with increased mRNA expression of matrix metalloproteinase-12 in the lungs and increased protein levels of Tumor Necrosis Factor-α in the BAL fluid of CS-exposed Balb/c and scid mice compared to air-exposed littermates." (PMID 16359546, 2005). "In addition, TNF-α is associated with the development of emphysema in mice when exposed to cigarette smoke." (PMID 37240069, 2023). "Two markers of systemic inflammation, TNFα and IL-1β, were independently associated with emphysema in PLWH and may contribute to the pathogenesis of emphysema." (PMID 33936110, 2021). "In a logistic regression model adjusted for age, sex, ethnicity, smoking status, BMI and CD4 nadir, elevated TNFα (adjusted odds ratio (aOR): 1.78 [95%CI: 1.14-2.76], p=0.011) and IL-1β (aOR: 1.81 [95%CI: 1.16-2.81], p=0.009) were independently associated with emphysema." (PMID 33936110, 2021). "The miRNA-181 cluster has been associated with regulation of TNF-alpha, T-cell aging and emphysema." (PMID 34512723, 2021). "Of note, IL-1β was the only cytokine associated with visual emphysema, suggesting that IL-1β may be a more clinically relevant biomarker than TNFα." (PMID 33936110, 2021). "Furthermore, the increase in TNF-α levels along time was associated with the increased number of apoptotic cells, which shows a disease progression in this emphysema model." (PMID 27536247, 2016). "We also found an association between the TNF rs1800629 SNP and paraseptal emphysema." (PMID 23734748, 2013). "Alternatively, the association between elevated TNFα and IL-1β and emphysema could reflect an upregulation of systemic inflammation which, in turn, could enhance inflammation in the lungs and accelerate the destruction of lung parenchyma and lead to emphysema in PLWH." (PMID 33936110, 2021).
emphysema (continued). "Thus, the observed association between elevated peripheral TNFα and IL-1β with emphysema, may be a consequence of a spill-over of cytokines from the affected lung tissue, where the cytokines are most active, and into the systemic circulation." (PMID 33936110, 2021). "In addition, emphysema has been associated with apoptosis in the cells of the alveolar wall, suggesting a possible mechanism through which TNF might contribute to emphysema development." (PMID 34829866, 2021). "These include IL-1β, which has similar amplifying effects to TNF-α; IL-6, whose concentrations are increased in emphysema patients and/or during exacerbations; IL-11; and IL-17." (PMID 41007683, 2025). "TNF-α and IL-1β have been identified as pivotal cytokines with prominent roles in airway remodeling and the development of emphysema, capable of initiating inflammatory cascades during COPD exacerbations." (PMID 41377050, 2025). "The expression of potent inflammatory cytokines such as IL-1β and TNF-α increases with exposure to cigarette smoke and can play a key role in the development of airway inflammation and emphysema." (PMID 39591423, 2024). "Serine proteases in the emphysema model, such as EcTI and BbKI, showed a reduction in TNF-α levels after treatment with these protease inhibitors." (PMID 37511021, 2023). "Tobacco smoke can strongly induce the TNFα gene, which is involved in the onset and progression of emphysema and COPD." (PMID 37454739, 2023). "TNF-α promotes the increased production of MMPs, which are involved in the development of emphysema." (PMID 37240069, 2023). "AZ11557272, a dual MMP-9 and MMP-12 inhibitor, abolishes smoke-induced lavage inflammatory cells and serum tumor necrosis factor α (TNFα), ameliorates morphological emphysema targets of COPD, and participates in the therapeutic process." (PMID 37175113, 2023). "The inflamed lung releases proteases such as matrix metalloprotease and elastase, which can lead to emphysema, and pro-inflammatory mediators like tumor necrosis factor (TNF)-α, interleukin (IL)-1β, IL-8, and IL-17 that attract inflammatory cells." (PMID 36678340, 2023). "A recent study found that theaflavin-3,3′-digallate attenuated emphysema in mice by suppressing necroptosis and significantly decreased the TNF-α and IL-1β levels." (PMID 36979417, 2023). "For these studies, the blockade of TNFα is considered to be a therapeutic strategy against emphysema and COPD." (PMID 37454739, 2023). "TNF-α was described as the main initiator or mediator of cigarette smoke-induced emphysema and therefore contributed to the degradation of the lung tissues in COPD." (PMID 36518817, 2022). "We observed that mice with PPE-induced emphysema showed increased levels of TNF-α, KC, and LDH in BALF." (PMID 36012176, 2022). "Increasing levels of TNF-α worsen the severity of emphysema via recruiting inflammatory cells and then degrading more alveolar walls, especially during the period of exacerbation." (PMID 35665319, 2022). "Similar to previous studies, the expression of ROS, IL‐8, and TNF‐α in our mice exposed to long‐term CS was elevated, which was associated with a reduction in HDAC‐2 activity and emphysema‐like pulmonary destruction." (PMID 34327862, 2021). "Furthermore, we are unable to determine whether the observed association between elevated plasma concentrations of TNFα and IL-1β and radiographic emphysema in PLWH is due to local inflammation in the lung or rather reflects a more general state of chronic systemic inflammation." (PMID 33936110, 2021). "We further examined the levels of mRNA expression from pro-inflammatory cytokines (IL-1β and TNF-α) and an anti-inflammatory cytokine (IL-10) in the whole lungs of an emphysema model." (PMID 34425800, 2021).
emphysema (continued). "PLWH with emphysema had higher concentrations of TNFα (median (IQR): 8.2 (6.4-9.8) versus 7.1 (5.7-8.6) pg/ml, p<0.001), IL-1β (0.21 (0.1-0.4) versus 0.17 (0.1-0.3) pg/ml, p=0.004) and IL-6 (3.6 (2.6-4.9) versus 3.1 (2.0-4.3) pg/ml, p=0.023) than PLWH without." (PMID 33936110, 2021). "Conversely, TGF-β signaling attenuation and TNF-signaling activation emerged as potentially novel functionaries of Cd9-deletion-induced emphysema." (PMID 33424923, 2020). "Another study showed that levels of TNF-α, IL-6, and IL-1β increased in sputum during emphysema in humans." (PMID 32963734, 2020). "PM significantly increased mice emphysema and airway inflammation measured by mean linear intercept, alveolar destroy index and total cell, neutrophil counts, cytokines IL-6, tumor necrosis factor (TNF)-α, CXCL1, IL-1β in bronchoalveolar lavage fluid." (PMID 32116706, 2020). "This has been also supported by mouse studies where mice overexpressing pulmonary TNF-α resulting in emphysema also exhibited increased plasma TNF-α and muscle wasting." (PMID 30155241, 2018). "Co-existence of emphysema and hyperplasia in pulmonary tissue was also observed in mice expressing TNF-α at elevated level." (PMID 28860943, 2017). "Alternatively, it has been reported that patients with emphysema have elevated plasma levels of tumor necrosis factor-α and reactive oxygen species, which decrease the availability of nitric oxide (NO), an important vasodilator in muscle." (PMID 28143453, 2017). "The presence of macrophages is the main factor involved in emphysema because they release inflammatory mediators such as TNF-α, IL-6, and MMPs at the injury site." (PMID 26646821, 2015). "Another study demonstrated diminished levels of the pro-inflammatory cytokines TNFα, interleukin-1, interleukin-6 and interleukin-8 in rat pulmonary tissue following bosentan treatment of induced emphysema." (PMID 24342001, 2013). "In particular, polymorphisms in MMP9 and TGFB1 are proposed to protect against centrilobular emphysema, and polymorphisms in TIMP2 and TNF seem to increase the risk for paraseptal emphysema and/or airflow obstruction." (PMID 23734748, 2013). "TNF-α, which is expressed by macrophages and other resident lung cells, induces intracellular signaling events that promote the development of emphysema." (PMID 24101903, 2013). "The emphysema cells demonstrated minimal baseline CD62E expression (<5%) with a rightward shift in response to TNFα stimulation at 1 hour with approximately 30% cells staining positively for CD62E." (PMID 23425195, 2013). "We detected high values of MLI, great numbers of inflammatory infiltrates, and high levels of TNF-α and IL-8 in the lungs of smoking rats, demonstrating that heavy smoking-inuced emphysema and airway inflammation in the lungs of rats." (PMID 22701274, 2012). "The implication of IL-1β was also confirmed in an animal model, showing that cigarette smoke-induced emphysema was reduced in mice that were null for the receptors of IL-1β and TNF-α." (PMID 23300722, 2012). "TNF-α was also positively correlated with leptin/% FM in both chronic bronchitis and emphysema (r = 0.774, p < 0.001 and r = 0.499, p = 0.015 respectively)." (PMID 19344528, 2009). "This correlation between TNF-α and leptin was true even when we studied patients with chronic bronchitis and emphysema separately (r = 0.719, p < 0.001 and r = 0.505, p = 0.014 respectively)." (PMID 19344528, 2009). "Three of the 33 inflammatory markers, IL-6, MMP-7 and tumor necrosis factor alpha (TNF-α), were associated with quantitative emphysema." (PMID 19718453, 2009). "IL-6 was significantly higher in smokers with emphysema than in the other two groups while TNF values were similar in all groups, and CRP tended to be higher in smokers with or without emphysema (ANOVA, p = 0.077)." (PMID 17822550, 2007). "Lymphoid tissue and emphysema in the lungs of transgenic mice inducibly expressing tumor necrosis factor-alpha." (PMID 15585067, 2004).
emphysema (continued). "Also, TNF-α over-expresser mice developed emphysema with increased expression of MMP12 and the pro-inflammatory chemokines." (PMID 38771844, 2024). "We hypothesized that the downregulation mechanism for TNFα by L4 would also function in the emphysema mouse model." (PMID 37454739, 2023). "The infiltrated tissue around bronchioles that has been characterized in COPD patients showed the presence of CD4+ and CD8+ lymphocytes correlating with histologic lesions suggestive of emphysema, and clear signs of airway obstruction and cell destruction due to the release of perforins and TNFα." (PMID 37108906, 2023). "Importantly, IL-1β is involved in the development of emphysema and small airway remodeling in mice, with effects comparable to TNF-alpha." (PMID 37240069, 2023). "In the analysis using a transgenic mouse that expresses TNFα in alveolar type II cells under the control of the human surfactant protein C promoter, the overexpression of TNFα resulted in the development of pulmonary emphysema by the activation of the elastase." (PMID 37454739, 2023). "TNF-α, mainly produced by macrophages, can promote the expression of CXCL10, a potent chemoattractant recruiting neutrophils, monocytes, and T-helper type 1 cells, consequently, causing pulmonary emphysema." (PMID 35035511, 2022). "Similarly, decreases in TNF-α and KC levels were also reported in the lungs of emphysema mouse models upon the administration of hUC-MSCs." (PMID 36012176, 2022). "There are also data to support the role of INF-γ and TNF-α in pulmonary emphysema." (PMID 35163689, 2022). "Additionally, HDAC2 knockdown enhances the activity of NF-κBp65, thereby increasing IL-8 and TNF-α levels in murine emphysema model." (PMID 34322124, 2021). "In contrast, the association between elevated TNFα and emphysema did not persist in sensitivity analyses (aOR: 1.05, [95%CI: 0.50-2.20], p=0.895)." (PMID 33936110, 2021). "IL-1β and TNF-α stimulate macrophage and bronchial epithelial cells to produce matrix metalloprotein-9 and extracellular matrix protein-tenascin, respectively, which are involved in the pathogenesis of emphysema." (PMID 33915841, 2021). "To examine whether the emphysema-protective effect of PRMT6 was associated with an anti-inflammatory effect on the mice after CSE injection, we measured the levels of TNFα and IL-1β in the lung tissues." (PMID 32047419, 2020). "The morphological changes were also accompanied by an increase in lung lymphocytes, macrophages, macrophage-derived metalloproteases, neutrophils, neutrophil elastase, oxidants, IL-6, and TNF-α, all of which have been demonstrated to play significant roles in the pathogenesis of emphysema." (PMID 28737721, 2017). "Conversely, smoke-induced emphysema in mice is accompanied by low-grade inflammation and a slight decrease in muscle mass, whereas emphysema and a strong pulmonary and systemic inflammatory response in SP-C/TNF transgenic mice is accompanied by a marked reduction in body and muscle weight." (PMID 28464882, 2017). "The previous studies reported that both CS and LPS directly damaged airway epithelium and activated macrophages and lymphocytes to generate proinflammatory cytokines (such as TNF-α, IL-6, IL-8, and IL-1β), which then activated neutrophils, leading to chronic bronchial inflammation and emphysema." (PMID 27524867, 2016). "Among them, TNF-α showing chemotaxis effects on white blood cells, can trigger the occurrence of inflammatory response, and may participate in the formation of emphysema and damage of epithelial cells." (PMID 27832794, 2016). "Indeed, deletion of genes encoding the TNF-α receptor or IFN-γ protects mice from development of CS-induced emphysema, whereas TNF-α or IFN-γ overexpression leads to lung emphysema." (PMID 25962837, 2015). "It is known that TNF-α drive 70% of CS-induced emphysema in the mouse." (PMID 24058452, 2013).
emphysema (continued). "In particular, emphysema defined by parenchymal voxels with computed attenuation values less than −950 Hounsfield Units (HU) was associated with higher blood levels of IL-6 and MMP-7, but lower TNFα levels." (PMID 23577098, 2013). "CD31 positive cells from 3 patients with emphysema were selected at random and thereafter stimulated with 1 ng/ml TNFα for 1 hour and stained for CD62E to investigate whether these cells were microvascular in origin." (PMID 23425195, 2013). "Although no natural animal models of COPD exist, intraperitoneal injection of TNF-alpha in rats leads to emphysema, which may resemble the apoptosis of alveolar cells observed in COPD patients with emphysema." (PMID 22300528, 2012). "Furthermore, we found that treatment with erythromycin mitigated the smoking-induced emphysema and reduced the numbers of inflammatory infiltrates and levels of TNF-α and IL-8 in the lungs of rats." (PMID 22701274, 2012). "Interferon-gamma (IFN-γ) and tumor necrosis factor-alpha (TNF-α) are the main proinflammatory cytokines contributing to Th1-driven inflammation, which often results in neutrophilic infiltration with mucus hypersecretion and tissue damage, eventually leading to chronic bronchitis and emphysema." (PMID 39063652, 2024). "In our study, one explanation for the mitigation of the emphysema was decreased levels of pro-inflammatory factors in the lungs (IL-1β and CXCL1/KC) and circulation (TNF-α, IL-1β, and IL-17A) by hUC-MSCs which may associate with the reduction of the neutrophil infiltration in emphysematous mice." (PMID 34646841, 2021). "TS-COPD has much greater emphysema which may be related to increased TNF-α level." (PMID 33915841, 2021). "However, this increase in aerated lung volume could also be pathologic resembling the emphysema-like phenotype in the SPC/TNF-Tg mice." (PMID 29320550, 2018). "In addition, mice overexpressing TNFα in lung tissue develop chronic inflammation and emphysema." (PMID 23533311, 2013). "The latest study also found that mast cells stimulate macrophages to release TNF-α by secreting chymase-1 in COPD, which further reflects the active interaction of immune cells in emphysema." (PMID 36248880, 2022). "Administration of TNF-α induces pathologic features typical of COPD in animal models, with similar inflammatory cell infiltrate in the lungs, which leads to emphysema." (PMID 33915841, 2021). "TNF-α, can induce the production of CXCL10, a potent chemoattractant for leukocytes such as monocytes, neutrophils and Th1 cells, and thus induces pulmonary emphysema." (PMID 34784929, 2021). "The relative mRNA levels of TNF-α, IFN-γ, IL-8, IL-18, IRF-5, and TGF-β increased in the emphysema mice." (PMID 32681029, 2020). "Inflammatory mediators and chemotactic factors, including tumor necrosis factor-α (TNF-α), interleukin- (IL-) 6, and IL-10, which is mediated in part by the p38 MAPK pathway, contribute to the formation of pulmonary emphysema." (PMID 29234369, 2017). "Levels of proinflammatory cytokines (TNF-α and IL-6) that may mediate muscle wasting, although low, were significantly increased in the limb muscle of tumor-bearing animals without underlying emphysema (U group)." (PMID 27549759, 2016). "TNF-α also increased from ELA at 4 weeks to ELA-S at 8 weeks, depicting a time dependence of this emphysema model, similar to that described in an in vitro model." (PMID 27536247, 2016). "Since TNF-α and MMP-9 play important roles in the pathogenesis of emphysema, we examined their expressions in lung tissue." (PMID 26646821, 2015). "We predicted 39 molecular changes mostly related to inflammatory processes including known key emphysema drivers such as NF-κB and TLR4 signaling, and increased levels of TNF-α, CSF2, and several interleukins." (PMID 25962837, 2015). "Recently, TNFα has been described as the “driving force behind COPD”, and induction of TNFα in the lung has been shown to result in emphysema in the mouse model." (PMID 23731729, 2013).